TNF (tumor necrosis factor)
Diseases named in the same sentence as TNF in open-access papers (continued):
Sharing a sentence is not in itself a finding about the gene and the disease.
lupus (477 papers, 2005 to 2026). "The primary approach in the treatment of anti‐TNF‐α lupus‐like paradoxical reactions is discontinuation of the causative agent." (PMID 39816706, 2025). "Lupus-like symptoms have been reported following initiation of TNF inhibitors (e.g., infliximab, etanercept), although a causal relationship remains difficult to establish." (PMID 41375587, 2025). "There are more reports of lupus-like reactions caused by TNF-α inhibitors compared to other biologics." (PMID 39618670, 2024). "Tumor necrosis factor inhibitors were avoided due to the risk of systemic lupus erythematosus (SLE)-like drug eruption." (PMID 39262502, 2024). "How mutated IL-18 and TNFα gene polymorphisms regulate the mRNA expression of IL-18 and TNFα and then be involved in lupus pathogenesis needs discussion." (PMID 38164134, 2023). "The occurrence of antinuclear antibodies (ANA) and the induction of lupus have also been linked to anti-TNF-α agents, including IFX and ADA." (PMID 36145514, 2022). "Etanercept (Enbrel), a soluble TNF p75 receptor that acts as a TNF-α antagonist by inhibiting TNF-α interaction with its cell surface receptor, significantly decreased systemic inflammation and bone loss in the FcγRIIb-/- lupus model." (PMID 33861790, 2021). "Some genes in the CNV deletion regions were significantly associated with systemic lupus erythematosus, such as tumor necrosis factor (TNF) in chromosome 6 and small RNA binding exonuclease protection factor La (SSB) in chromosome 2." (PMID 34723755, 2021). "The pathogenesis has not been fully elucidated although type I interferons (IFN-α) and plasmacytoid dendritic cells seem implicated in several TNF-induced skin eruptions including paradoxical psoriasis, psoriasiform dermatitis, and lupus." (PMID 33802483, 2021). "Various inflammatory cytokines, including interleukins (IL-6, IL-17, and IL-18), type I interferons, and tumor necrosis factor-α (TNFα) have been implicated in the pathogenesis of lupus." (PMID 33953971, 2021). "KEGG pathways enriched by these hub genes included systemic lupus erythematosus, alcoholism, osteoclast differentiation, and TNF signaling pathway have been reported to be associated with KD." (PMID 33868359, 2021). "Linking these data to human disease, anti-TNF treatment has been associated with lupus-like symptoms as well as an induction of IFN signature in peripheral blood." (PMID 33441439, 2021). "Clinicians using anti‐TNF medications should counsel patients about this potential risk and monitor for clinical manifestations of lupus during routine follow up." (PMID 32514462, 2020). "The expression of PD-L1 is deficient in the monocytes of patients with systemic lupus erythematosus, but can be reconstituted by the exogenous addition of TNF-α." (PMID 30646912, 2019). "Conversely, inhibition of TNF raises the risk of inducing lupus-like manifestations, as described here." (PMID 31052273, 2019). "In conclusion, our studies showed that anti-pneumococcal vaccination with Prevnar-13 associates with amelioration of disease severity in murine lupus, a phenomenon associated with reduced TNF-α and IL-6 production by B cells and increased TFR/TFH ratio." (PMID 31824490, 2019). "In TNF-α-deficient mice, we found that lupus IgG decreased the initial red pulp inflammation and further inhibited GC formation." (PMID 32082297, 2019). "The histopathology demonstrated that red pulp inflammation induced by lupus IgG was significantly decreased in TNF-α-deficient mice compared to wild-type (WT) mice." (PMID 32082297, 2019). "Administration of anti-TNF antibody is reported to attenuate lupus phenotypes in a murine lupus model with Fasl mutation and in an experimental lupus model." (PMID 31052273, 2019). "The IHC staining showed that GC formation induced by lupus IgG was also significantly reduced in TNF-α-deficient mice compared to WT mice." (PMID 32082297, 2019).
lupus (continued). "Obese lupus patients have increased gene and protein expression of several proinflammatory molecules such as the cytokines IL-23 and TNF-α, the latter being associated with total fat mass on the trunk region in pediatric lupus patients." (PMID 31137916, 2019). "TNF-α is a pro-inflammatory cytokine that is mainly produced by monocytes/macrophages; thus, the role of TNF-α in the development of lupus-associated liver lesions was investigated." (PMID 29988500, 2018). "We injected lupus-IgG intrahepatically into TNF-α-deficient mice (TNF-α−/−) and found that the liver lesions were significantly reduced in the TNF-α−/− mice." (PMID 29988500, 2018). "Our data demonstrate that liver inflammation induced by lupus IgG was remarkably reduced in mice with Kupffer cell depletion and TNF-α deficiency." (PMID 29988500, 2018). "Association between each of 135 genotyped SNPs in IFIH1 and four lupus-associated plasma mediators, IL-6, TNF-α, IFN-β, and IP-10, were investigated via linear regression." (PMID 28234905, 2017). "IRF5-deficient cDC exhibited a reduced ability to produce TNFα, IL-6, and IL-10 in lupus-prone mice." (PMID 27034965, 2016). "In RA, anti-TNF-α therapy is sometimes associated with adverse events, such as multiple sclerosis and lupus." (PMID 30873466, 2016). "As presented in this work, GM extract attenuates lupus-associated cardiac apoptosis in lupus-prone mice by down-regulating TNF-α/TNF-α receptors and Fas/FADD and reducing amounts of activated caspase-9, Bax, activated caspase-8 and activated caspase-3." (PMID 25985203, 2015). "Less frequently but more importantly, TNF antagonists can cause lupus manifestations in RA and rhupus syndrome." (PMID 24324510, 2013). "Previous studies have shown that TNF-α deficiency is an important trigger and driver of lupus-like autoimmunity in NZB/W mice." (PMID 24319531, 2013). "Treatment with TNFα increases survival in lupus-prone mice and loss of Tnf or Tnf receptors accelerates disease." (PMID 23557436, 2013). "Dysregulation of TNF-α production has been implicated in a variety of human diseases, including lupus." (PMID 22761632, 2012). "An association between the use of TNF-α-blocking therapy and the induction of systemic lupus erythematosus and discoid lupus erythematosus is strongly suggested by the number of cases that have been published." (PMID 15899052, 2005). "It is unclear whether TNF inhibitors induce de novo lupus or simply unmask preexisting, subclinical lupus in genetically or immunologically predisposed individuals." (PMID 41375587, 2025). "The mechanisms underlying TNF-α inhibitor–induced lupus are less well understood but may involve IL-10 upregulation, B-cell hyperactivity, T-helper 2 (Th2)–driven B-cell activation or reduced cytotoxic T-cell apoptosis." (PMID 41283475, 2025). "Furthermore, an association between reduced anti-TNF autoantibody levels and lupus flares has been observed." (PMID 41117951, 2025). "Those literature works indicated that anti-tumor necrosis factor treatment may increase the risk of lupus in women." (PMID 38333008, 2024). "For instance, anti-TNF-α inhibition has been associated with acute infusion reactions (which include symptoms like headache, fever, chills, urticaria, chest pain), infections, tumor development and few cases of drug-induced lupus, seizures, and pancytopenia." (PMID 38201258, 2023). "Finally, it is worth to mention that anti-TNF drugs, such as infliximab, have been demonstrated to cause clinical symptoms that mimic lupus in treated patients." (PMID 38022524, 2023). "Innate immune stimulus induces lupus-associated autoantibody production in TNF-deficient mice." (PMID 35104241, 2022). "One study has demonstrated the suppressive capabilities of CB2R selective agonists on pDC production of IFN-α and TNF-α, which are elevated in autoimmune conditions such as systemic lupus erythematosus and may also be implicated in DM pathogenesis." (PMID 34983619, 2022).
lupus (continued). "IL-10, TNF-α and IL-6 have been implicated in lupus pathogenesis." (PMID 36505418, 2022). "Additionally, some TNF gene polymorphisms in Mexican patients were associated with systemic lupus erythematosus (SLE) and lupus nephritis." (PMID 33670423, 2021). "Etanercept treatment was used to evaluate whether TNF-α is a key mediator of mandibular bone loss and to test whether TNF-α blockade can reverse this phenotype in the FcγRIIb-/- lupus model." (PMID 33861790, 2021). "The present study aimed to investigate whether TNF-α is a key mediator of mandibular bone loss in the FcγRIIb-/- model of lupus." (PMID 33861790, 2021). "The aim of the present study was to investigate whether an anti-TNF-α antagonist could prevent mandibular bone loss in the FcγRIIb-/- mouse model of lupus." (PMID 33861790, 2021). "However, a study from a multiethnic lupus cohort showed that specific TNF variants and leukopenia influenced the risk of developing pneumonia, regardless of immunosuppressive therapy." (PMID 30994732, 2019). "Although the mechanisms associated with TNF-inhibitor-induced lupus remain uncertain, several mechanisms have been hypothesized." (PMID 31052273, 2019). "We found that in lupus mice, IgG is an important pathological factor in red pulp inflammation and GC responses; pathogenic lupus IgG promoted GC formation through the macrophage-mediated secretion of TNF-α." (PMID 32082297, 2019). "Furthermore, we found that pathogenic lupus IgG promotes inflammation and GC formation through the macrophage-mediated secretion of TNF-α." (PMID 32082297, 2019). "Additionally, when these lupus-prone mice were crossed into a TNF deficient background, they experienced aggravated disease." (PMID 29751683, 2018). "A proliferation inducing ligand (APRIL) is a member of the tumor necrosis factor (TNF) superfamily mediating antibody-producing plasma cell (PC)-survival that may be involved in the duration of pathogenic autoantibodies in lupus." (PMID 22355399, 2012). "Previous studies have reported that the TNF signaling pathway plays a role in postmenopausal osteoporosis and systemic lupus erythematosus (SLE)-associated osteoporosis." (PMID 40241795, 2025). "Thus, dysregulated expression of both HVEM and TNFR2 and the association of the lupus epigenetic signature with transcriptional activation of TNF-α signaling suggest a complex environment in which multiple cytokines, potentially TNF-α or LIGHT, affect the molecular biology of Th cells." (PMID 39688922, 2024). "By contrast, although anti-TNF therapy can induce remission of refractory nephritis, TNF deficiency is associated with induction of systemic lupus erythematosus (SLE) in more than one mouse model." (PMID 35104241, 2022). "Heterozygous mutants and minor alleles of TNF-α (G-238A and G-308A) polymorphisms were significantly higher in SLE patients compared to healthy controls and associated with development of lupus nephritis." (PMID 31409832, 2019). "TNF-α (G-308A and G-238A) variants and minor alleles were more frequent in SLE cases and lupus nephritis cases suggesting an important role of TNF-α variants with predisposition to SLE and clinical manifestations." (PMID 31409832, 2019). "Moreover, TNF deficiency aggravates immune-complex deposition in the kidney associated with increased number of plasmacytoid DCs and elevated levels of type I interferons in a pristane-induced lupus model." (PMID 31052273, 2019). "We analysed the possible association of TNF-α polymorphisms with clinical manifestations of SLE, namely lupus nephritis which is one of the major clinical phenotypes linked to SLE mortality." (PMID 31409832, 2019). "TNF-α inhibitors remain the therapeutic class most often associated with ANA seroconversion, anti-dsDNA induction, anti-TNF-induced lupus, CLE exacerbation, and SLE flares, highlighting the need for careful risk–benefit assessment in lupus-prone settings." (PMID 41596733, 2026).
lupus (continued). "TNF-α inhibitors showed the strongest association with ANA seroconversion, anti-dsDNA induction, drug-induced lupus, and lupus flares." (PMID 41596733, 2026). "Background/Objectives: A case-control study was conducted to determine the association of the −238 G>A and −308 G>A TNF-alpha (TNFA) promoter polymorphisms with mRNA and protein expression in 180 Systemic Lupus Erythematosus (SLE) patients and 186 control subjects (CS) from western Mexico." (PMID 40507454, 2025). "TNF-α inhibitors such as infliximab and adalimumab are occasionally used in pemphigoid and lupus with periocular inflammation, though clinical responses remain variable." (PMID 41373875, 2025). "Key immune response processes, including tumor necrosis factor (TNF) production, phagocytosis, and complement cascades, as well as systemic lupus erythematosus (SLE)-associated pathways, were enriched in the upregulated group." (PMID 40428335, 2025). "Recent studies in mice have enhanced our understanding of how several pro-inflammatory cytokines, including interferon (IFN)-I, tumor necrosis factor (TNF)-α, and interleukin (IL)-6, inhibit the development and generation of lupus B cells." (PMID 39917309, 2025). "This is different from what happens in systemic lupus erythematosus and other inflammatory diseases, where TNF-α levels go up as albumin levels go down." (PMID 41011058, 2025). "TNF inhibitor-induced lupus often resolves after drug discontinuation, supporting a drug-related effect." (PMID 41375587, 2025). "IL-1 has been shown to potentiate the effects of TNF-α and IL-6, worsening mucosal tissue damage in lupus patients." (PMID 40791585, 2025). "The mechanism by which TNF‐α antagonists induce lupus‐like paradoxical reactions (L‐PRs) remains poorly understood." (PMID 39816706, 2025). "Probiotics like L. rhamnosus LC-STH-13 inhibit NF-κB activation by blocking TLR9 signaling and preventing IκBα degradation, thus reducing pro-inflammatory cytokines such as TNF-α, IL-6, and IL-1β in lupus-prone mice." (PMID 40534849, 2025). "The prevalence of anti‐TNF therapy‐induced Lupus‐like paradoxical reactions is rare, estimated to occur in approximately 0.5%–1% of treated patients." (PMID 39816706, 2025). "While existing studies reinforce TNF-α’s inflammatory contribution in lupus, its mechanistic involvement in Treg dysfunction and vascular endothelial activation warrants in-depth exploration using cell-specific gene deletion approaches." (PMID 41280899, 2025). "Nevertheless, in some cancers (e.g., breast cancer), TNF-α promotes tumor formation and may also cause autoimmune diseases such as multiple sclerosis, inflammatory bowel disease, rheumatoid arthritis, psoriatic arthritis, and systemic lupus erythematosus (SLE)." (PMID 41226575, 2025). "Lupus‐like paradoxical reactions (L‐PRs) induced by TNF‐α inhibitors are relatively uncommon but have been well documented." (PMID 39816706, 2025). "Studies have shown significantly elevated levels of TNF-α in saliva and serum samples from lupus patients with oral lesions, indicating its role in amplifying inflammatory responses in the oral mucosa." (PMID 40791585, 2025). "Reported renal complications of TNF-α inhibitors include drug-induced systemic lupus erythematosus, AAV, and IgA vasculitis." (PMID 39487903, 2025). "This postulation is further supported by a previous study demonstrating the inhibition of TNFα by SOCS1-KIR in the mrl/lpr rodent model of lupus." (PMID 39867889, 2024). "In keeping with these observations, patients with lupus prescribed ARBs were less likely to have the lupus-driven chromatin accessibility signature and had reduced transcriptional enrichment for the TNF-α signaling pathway." (PMID 39688922, 2024). "Genes involved in the TNF-α signaling pathway were enriched among lupus DARs in all subsets except Th1-like cells, which had high baseline enrichment in HCs." (PMID 39688922, 2024).
lupus (continued). "Our previous results demonstrated that lupus Th cells are enriched for cytokine signaling pathways including TNF-α signaling, IFN-α response, and IFN-γ response gene sets and we focused on these genes." (PMID 39688922, 2024). "TNF-α levels are increased in lupus patient plasma, and elevated levels of sTNFR1 and sTNFR2 predate lupus nephritis flares." (PMID 39688922, 2024). "In these group 1 lupus individuals, there was reduced CD28 expression on Th cells, an effect that has been linked to TNF-α signaling." (PMID 39688922, 2024). "Consistent with previous findings, the abundance of phosphorylated ERK, IL-1β, and TNFα proteins in the DRG of lupus mice was notably higher compared to normal controls." (PMID 38612414, 2024). "Cases of drug-induced lupus developing from long-term administration of tumor necrosis factor alpha (TNFα) inhibitors are rare, so we report this case with a literature review." (PMID 39618753, 2024). "Transcriptionally, TNF-α signaling was highly enriched in lupus Th populations along with other cytokine pathways compared with healthy cells." (PMID 39688922, 2024). "Similar to TWEAK, LIGHT levels are correlated to the TNF-α transcriptional signature and thus implicated in TNF-α signaling responses in lupus subgroups." (PMID 39688922, 2024). "In systemic lupus erythematosus (SLE), TNF-α’s role remains controversial, yet it is associated with higher levels of autoantibodies and kidney damage." (PMID 38474052, 2024). "Transcriptional activation of TNF signaling in lupus Th cells correlated with plasma levels of TNF family cytokines, including TWEAK, and with protein dysregulation of TNF family receptors, including HVEM (herpes virus entry mediator: TNFRSF14)." (PMID 39688922, 2024). "The 233 lupus DARs demonstrated significant enrichment of expected pathways, including cytokine production and tumor necrosis factor production." (PMID 39688922, 2024). "Anti-TNF-α therapy can also shift the immune system to Th-2, upregulating the production of antibodies, including anti-nuclear, anti-dsDNA, and anti-neutrophil cytoplasmic antibodies, which may lead to the development of lupus-like and/or crescentic glomerulonephritis in susceptible individuals." (PMID 39421866, 2024). "TWEAK was likewise strongly correlated to the transcriptional activation of TNF-α signaling in naive Th cells of patients with lupus." (PMID 39688922, 2024). "Levels of LIGHT also significantly correlated with T cell TNF-α signaling enrichment across patients with lupus." (PMID 39688922, 2024). "The heterogeneity in TNF-α signaling, potentially linked to ARB usage, in epigenetically distinct patients is noteworthy given the complex relationship between TNF-α and lupus." (PMID 39688922, 2024). "Among the 637 peak-gene linkages unique to lupus, 78 ATAC-Seq peaks were linked to 29 genes in the TNF-α signaling pathway, including TNFAIP3." (PMID 39688922, 2024). "Increased expression of many TNF-α signaling genes, including RELB, accompanied the TNF-related enrichment in group 1 lupus participants." (PMID 39688922, 2024). "While cases of drug-induced lupus by TNF-alpha inhibitors have been extensively documented, this report represents the first instance of NuMA-1 antibody induction." (PMID 39628740, 2024). "Cutaneous disease in murine lupus models is, in part, driven by members of the tumor necrosis factor (TNF) and TNF-receptor (TNFR) superfamilies." (PMID 38660315, 2024). "Naive and effector Th cells in most patients with lupus have enhanced chromatin accessibility with parallel transcriptional changes surrounding cytokine signaling pathway genes, including the TNF signaling family." (PMID 39688922, 2024). "In the case of anti-TNF-α therapies in SLE, the possibility of ATIL (anti-TNF-induced lupus) is a serious concern that limits their use." (PMID 37833861, 2023).